TNFAIP6 (TNF alpha induced protein 6)
Description:
Major regulator of extracellular matrix organization during tissue remodeling. Catalyzes the transfer of a heavy chain (HC) from inter-alpha-inhibitor (I-alpha-I) complex to hyaluronan. Cleaves the ester bond between the C-terminus of the HC and GalNAc residue of the chondroitin sulfate chain in I-alpha-I complex followed by transesterification of the HC to hyaluronan. In the process, potentiates the antiprotease function of I-alpha-I complex through release of free bikunin. Acts as a catalyst in the formation of hyaluronan-HC oligomers and hyaluronan-rich matrix surrounding the cumulus cell-oocyte complex, a necessary step for oocyte fertilization. Assembles hyaluronan in pericellular matrices that serve as platforms for receptor clustering and signaling. Enables binding of hyaluronan deposited on the surface of macrophages to LYVE1 on lymphatic endothelium and facilitates macrophage extravasation. Alters hyaluronan binding to functionally latent CD44 on vascular endothelium, switching CD44 into an active state that supports leukocyte rolling. Modulates the interaction of chemokines with extracellular matrix components and proteoglycans on endothelial cell surface, likely preventing chemokine gradient formation. In a negative feedback mechanism, may limit excessive neutrophil recruitment at inflammatory sites by antagonizing the association of CXCL8 with glycosaminoglycans on vascular endothelium. Has a role in osteogenesis and bone remodeling. Inhibits BMP2-dependent differentiation of mesenchymal stem cell to osteoblasts. Protects against bone erosion during inflammation by inhibiting TNFSF11/RANKL-dependent osteoclast activation.
Synonyms: TSG-6; TSG6
Tractability: Antibody: UniProt places it where antibodies can reach, with high confidence; its Gene Ontology location is reachable by antibodies, with high confidence; UniProt predicts a signal peptide or a membrane-spanning region.
Gene: Protein-coding gene on chromosome 2 (151,357,592 to 151,380,046, forward strand). Ensembl gene ENSG00000123610.
Subcellular location: Secreted
Pathways (Reactome):
Immune System: Neutrophil degranulation
Gene Ontology:
Molecular function: calcium ion binding; carboxylesterase activity; fibronectin binding; hyaluronic acid binding; protein binding
Biological process: fibronectin fibril organization; hyaluronan metabolic process; negative regulation of BMP signaling pathway; negative regulation of inflammatory response; negative regulation of neutrophil chemotaxis; negative regulation of osteoblast differentiation; negative regulation of osteoclast differentiation; positive regulation of receptor clustering; cell-cell signaling; inflammatory response; ovarian cumulus expansion; signal transduction; cell adhesion; positive regulation of cell migration
Cellular component: extracellular region; ficolin-1-rich granule lumen; tertiary granule lumen
Genetic constraint (gnomAD): Loss-of-function variants: 24 observed, 24.91 expected, observed/expected ratio (o/e) 0.96, 90% interval 0.7 to 1.36. The upper end of that interval is the gene's LOEUF score, 1.36, which puts it in group 5 of 6, group 1 being the genes least tolerant of losing a copy. Missense variants: 226 observed, 284.33 expected, observed/expected ratio (o/e) 0.79, 90% interval 0.71 to 0.89. Synonymous variants: 97 observed, 100.22 expected, observed/expected ratio (o/e) 0.97, 90% interval 0.82 to 1.15.
Homologues: Orthologues: chimpanzee TNFAIP6 (99% identical), macaque TNFAIP6 (97% identical), guinea pig TNFAIP6 (95% identical), rabbit TNFAIP6 (94% identical), dog TNFAIP6 (92% identical), pig TNFAIP6 (92% identical), mouse Tnfaip6 (90% identical), rat Tnfaip6 (89% identical), tropical clawed frog tnfaip6 (70% identical), zebrafish tnfaip6 (64% identical). Paralogues in human: STAB2 (31% identical), STAB1 (30% identical).
Diseases named in the same sentence as TNFAIP6 in open-access papers:
TNFAIP6 is named in the same sentence as 182 diseases in open-access papers, as found by Europe PMC text mining. Sharing a sentence is not in itself a finding about the gene and the disease. The quoted sentences say what the papers report.
colitis (29 papers, 2016 to 2025). Inflammation of the colon. "BM-MSCs lost the therapeutic effect of colitis after Tnfaip6 was knocked down in the IBD mice model." (PMID 34707499, 2021). "The serum Tnfaip6 concentration of colitis mice was higher than that of the normal mice." (PMID 34707499, 2021).
Arthritis (23 papers, 2012 to 2025). Inflammation of a joint. "Previous studies have reported that TNFAIP6 has anti-inflammatory effects in an experimental mouse model of arthritis, but further evidence to support this observation is lacking." (PMID 39185422, 2024). "Among these, Tnfaip6 plays a key role in several immune diseases, such as type 1 diabetes, arthritis, and IBD." (PMID 34707499, 2021). "TNFAIP6 is thought to play an anti-inflammatory role in arthritis and protect destruction of joint cartilage, which has been demonstrated in many arthritis mice models." (PMID 34177888, 2021). "The chondroprotective effect of TNFAIP6 in arthritis is mediated through the inhibition of MMPs and aggrecanase enzymes that damage cartilage." (PMID 23028973, 2012). "The LINK module of TNFAIP6 can interact with the extracellular matrix components glycosaminoglycan and hyaluronan and can have chondroprotective effects in various models of inflammation and arthritis." (PMID 23028973, 2012).
peritonitis (22 papers, 2012 to 2025). Inflammation of the peritoneum (tissue that lines the abdominal wall and covers most of the organs in the abdomen). "In a corneal injury model and a peritonitis mouse model, TNF alpha-induced protein 6 (TSG-6) secreted by MSCs effectively inhibits the entry of neutrophils into the injury site, thereby significantly reducing inflammatory responses." (PMID 37833933, 2023).
rheumatoid arthritis (16 papers, 2012 to 2025). A chronic, systemic autoimmune disorder characterized by inflammation in the synovial membranes and articular surfaces. "Enhanced levels of TNFAIP6 protein have also been found in the synovial fluid of patients with osteoarthritis and rheumatoid arthritis." (PMID 24000795, 2013). "For example, tumour necrosis factor, alpha-induced protein 6 (TNFAIP6), which is found in the synovial fluid of patients with osteoarthritis and rheumatoid arthritis was up-regulated in DD." (PMID 23554969, 2013). "TNFAIP6, which plays a critical role in osteogenesis and bone remodeling, has previously been explored to be up-regulated in the synovial fluid of patients with rheumatoid arthritis." (PMID 36928613, 2023). "Moreover, enhanced levels of TNFAIP6 are found in the synovial fluid of patients with osteoarthritis and rheumatoid arthritis." (PMID 30811458, 2019).
acute pancreatitis (15 papers, 2018 to 2025). An acute inflammatory process that leads to necrosis of the pancreatic parenchyma. "In addition, TNFAIP6 is also an inflammatory mediator in several autoimmune diseases and cancers, atherosclerosis, acute pancreatitis, type‐1 diabetes, osteoarthritis, acute lung injury and glioblastoma." (PMID 39704340, 2025). "Notably, TNFAIP6 secreted from human adipose tissue-originated mesenchymal stem cells is able to ameliorate severe acute pancreatitis in mice by downregulating endoplasmic reticulum stress." (PMID 35741777, 2022). "Furthermore, TNFAIP6 has been found to have therapeutic effects in a variety of disease models, such as atherosclerosis, acute pancreatitis, type‐1 diabetes, and acute lung injury." (PMID 35766985, 2022).
inflammatory bowel disease (14 papers, 2018 to 2025). A spectrum of small and large bowel inflammatory diseases of unknown etiology. "Tumor necrosis factor-induced protein 6 (TNFAIP6) secreted by bone marrow–derived MSCs attenuates inflammatory bowel disease by modulating follicular helper T cells and follicular regulatory T cells balance in mice." (PMID 37784129, 2023).
brain injury (11 papers, 2014 to 2025). Acute and chronic (see also brain INJURIES, CHRONIC) injuries to the brain, including the cerebral hemispheres, CEREBELLUM, and brain STEM. "TNFAIP6 has also been linked to traumatic brain injury in other research." (PMID 35766985, 2022).
colorectal cancer (10 papers, 2013 to 2025). A primary or metastatic malignant neoplasm that affects the colon or rectum. "TNFAIP6 is also a biomarker in colorectal cancer patients who have increased expression in peripheral blood cells relative to controls." (PMID 33983928, 2021). "This study shows that TNFAIP6 mRNA is elevated in peripheral blood cells of colorectal cancer patients." (PMID 23536776, 2013). "Recently, transcriptional profiling of blood from colorectal patients and normal controls by qRT-PCR identified TNFAIP6 as a biomarker for colorectal cancer." (PMID 23536776, 2013). "Besides, TNFAIP6 facilitates aggressiveness in a CD44-dependent manner to enhance metastasis in colorectal cancer." (PMID 38376551, 2024). "Interestingly, recent reports have shown that over-expression of TNFAIP6 in colorectal cancer cells results in tumor migration and invasion both in vitro and in vivo." (PMID 39342193, 2024). "Several studies showed that TNFAIP6 can promote metastasis in gastric and colorectal cancers." (PMID 38204755, 2023). "Therefore, it is necessary to clarify further the potential biological relationship between TNFAIP6 and colorectal cancer." (PMID 34294834, 2021).
keloid (10 papers, 2010 to 2024). An irregularly shaped, elevated mark on the skin caused by deposits of excessive amounts of collagen during wound healing. "Five hub genes were linked to keloid recurrence, including CHI3L1, IL1RN, MMP7, TNFAIP3, and TNFAIP6." (PMID 37685578, 2023). "The qRT-PCR experiment was used for detecting the differential expression of five hub genes (CHI3L1, IL1RN, MMP7, TNFAIP3, and TNFAIP6) in recurrent and non-recurrent keloid tissues." (PMID 37685578, 2023). "In the present study, the hub genes (CHI3L1, IL1RN, MMP7, TNFAIP3, and TNFAIP6) were mainly involved in the regulation of inflammatory response, IL-17 signalling pathway, and TNF signalling pathway, which is consistent with previous findings in keloids." (PMID 37685578, 2023). "ACAN and TNFAIP6 were found to interact with hyaluronic acid in keloid fibroblasts when upregulated but are not well studied in keloid or skin." (PMID 32085797, 2020). "A statistically significant (P < .05) differential expression and a fold change of more than 2 were determined between keloid margin and internal control biopsy samples for 10 genes, including ACAN, ASPN, C5orf13, HIF1A, IGFBP7, INHBA, LGALS1, PTN, SERPINH1, and TNFAIP6." (PMID 20418938, 2010).
Sepsis (9 papers, 2018 to 2025). Sepsis is defined as life-threatening organ dysfunction caused by a dysregulated host response to infection. "We identified 25 predictive genes, including LILRA5 and TNFAIP6, which had previously been associated with sepsis in other research." (PMID 38968271, 2024). "The qPCR results suggested that GK and PFKFB3 might contribute to the progression of S. aureus-induced sepsis, and GK, CEACAM1, TNFAIP6, PSTPIP2, SOCS3, and IL18RAP might be closely linked with E. coli-induced sepsis." (PMID 31093495, 2019). "The qPCR results suggest that GK and PFKFB3 might contribute to the progression of S. aureus-induced sepsis, and CEACAM1, TNFAIP6, PSTPIP2, SOCS3, and IL18RAP might be closely linked with E. coli-induced sepsis." (PMID 31093495, 2019). "Upregulation of TNFAIP6 and PLSCR1 was validated using public monocyte datasets and real-time PCR of mouse PBMCs, with PLSCR1 showing markedly increased expression in SLE cases complicated by sepsis." (PMID 41462079, 2025).
gastric cancer (8 papers, 2021 to 2024). A primary or metastatic malignant neoplasm involving the stomach. "It had been demonstrated that high TNFAIP6 expression is significantly associated with aggressive pathological features in urothelial cancer and gastric cancer." (PMID 34012914, 2021). "Previous research has indicated that elevated TNFAIP6 expression may be linked to unfavorable prognosis in malignant tumors such as OSCC, gastric cancer, and glioma." (PMID 39068492, 2024). "Downregulation of TNFAIP6 can inhibit the proliferation, invasion, and metastasis of gastric cancer (GC)." (PMID 35480305, 2022). "In addition, overexpression of TNFAIP6 was also found to increase with tumor invasion and lymph node metastasis in gastric cancer." (PMID 35631431, 2022).
breast carcinoma (7 papers, 2015 to 2024). "On the other hand, a positive correlation was found between TNFAIP6 gene expression and neutrophil and macrophage infiltration in all breast cancer subtypes, including Basal, Her2, Luminal A, and Luminal B, as well as with dendritic infiltration except in the case Luminal B patients." (PMID 39765744, 2024). "It is indicated that TNFAIP6 is a prognostic-related cytokine in breast cancers." (PMID 30918839, 2019). "The protein expression levels of TNFAIP6, IFRD1, IFNGR1, and IRF6 were analyzed in 125 breast cancer samples and 18 normal samples by using the UALCAN dataset." (PMID 39765744, 2024). "The heat map tables show the correlation between immune cell infiltrations and TNFAIP6, IFRD1, IFITM2, IFNGR1, IRF6, and NFIL3 in breast cancer." (PMID 39765744, 2024). "Among which, IBSP, MMP9, TNFAIP6, DHRS3, RIPK4, and CD200 had a diagnose value for patients with breast cancer bone metastasis." (PMID 30918839, 2019). "The research of TNFAIP6, DHRS3, ASS1, RIPK4, VIM, and CD200 in breast cancer may indicate that those genes may play a crucial role in the development of breast cancer bone metastasis." (PMID 30918839, 2019). "Overall survival analysis showed that TNFAIP6, IFITM2, IFNGR1, and IRF6 expression levels were not significant, whereas IFRD1 (n = 568) indicated a significantly (p < 0.05) increased risk in Luminal A breast cancer patients, along with NFIL3 (n = 219) in Luminal B patients with similar significance." (PMID 39765744, 2024). "Besides some published potential biomarkers of breast cancer bone metastasis were identified in our study, we also detected some novel biomarkers or their relationship with breast cancer bone metastasis has never been reported, such as TNFAIP6, DHRS3, ASS1, RIPK4, VIM, CD200." (PMID 30918839, 2019).
glioblastoma (6 papers, 2015 to 2025). The most malignant astrocytic tumor (WHO grade IV). "TNFAIP6 was identified as a hub gene for glioblastoma that was significantly associated with the prognosis of tumour patients." (PMID 35766985, 2022). "This study found that TNFAIP6 plays a vital role in the occurrence and development of glioblastoma." (PMID 35766985, 2022). "Vice versa, transfection of the human glioblastoma cell line U-373 MG with a C/EBPD expression vector led to a significant upregulation of C3, CXCL9, CP, CCL3, TNFAIP6, and IL-6 mRNA levels." (PMID 26230261, 2015). "The four tumor-related genes (TNFAIP6, C15orf48, WSCD2, and CBLN1) were neither reported in ferroptosis-related reports nor in glioblastoma-related studies, which were first found by us." (PMID 35720126, 2022).
asthma (5 papers, 2014 to 2019). "TSG‐6, which is a hyaluronan‐binding protein encoded by TNFAIP6, has been found to be involved in eosinophilia and airway hyper‐responsiveness in a mouse model of asthma." (PMID 24994897, 2014).
autoimmune disease (5 papers, 2017 to 2025). A disorder resulting from loss of function or tissue destruction of an organ or multiple organs, arising from humoral or cellular immune responses of the individual to their own tissue constituents. "The association between autoimmune disease and TNFAIP2 variant rs1132339 is particularly noteworthy, as is the fact that TNFAIP6 variant rs1046668 appears to follow a recessive inheritance pattern." (PMID 32951330, 2020).
lung carcinoma (5 papers, 2020 to 2025). "It is uncovered that TNFAIP6 expression is elevated in HIF-1α-induced lung cancer cells." (PMID 38376551, 2024). "TNFAIP6 expression has been discovered to be elevated in HIF-1α-induced lung cancer cells." (PMID 38376551, 2024). "The expression of the lung cancer stem cell marker CD44 and TGF-β ligand TGFB1 was also reduced by the depletion of TNFAIP6 in active PLK1-expressing cells." (PMID 31548612, 2020). "The effect of TNFAIP6 on lung cancer and its TIME has not been reported yet." (PMID 38204755, 2023).
ovarian carcinoma (5 papers, 2013 to 2024). A malignant neoplasm originating from the surface ovarian epithelium. "We demonstrated three potential biomarkers—CRABP2, SPP1, and TNFAIP6, which are higher in ovarian cancer and associated with poor prognosis." (PMID 35578123, 2022). "It indicates that TNFAIP6 can be an important regulator of ovarian cancer, and its property of being a hub enhances the original observation." (PMID 24292935, 2014). "In the original study, TNFAIP6 (tumor necrosis factor, α-induced protein 6) identified in our analysis as hub gene was 29.1-fold overexpressed in tumor endothelium, and was suggested to be specific for ovarian cancer vasculature." (PMID 24292935, 2014). "Therefore, TNFAIP6 is weaker in the practice of diagnosis of ovarian cancer." (PMID 35578123, 2022). "The other two genes, CRABP2 and TNFAIP6, have not been reported as biomarkers of ovarian cancer." (PMID 35578123, 2022).
Cerebral ischemia (4 papers, 2023 to 2025). Restriction of arterial blood supply to the brain associated with insufficient oxygenation to support the metabolic requirements of the tissue. "This study aimed to investigate the relationship between tumor necrosis factor alpha‐induced protein (TNFAIP6/TSG‐6) and astrocytes in cerebral ischemia/reperfusion (I/R) injury." (PMID 40130432, 2025).
COVID-19 (4 papers, 2021 to 2024). A disease caused by infection with severe acute respiratory syndrome coronavirus 2. "Yet, in contrast to FCGR3B, the expression of TNFAIP6 (indicator of COVID-19 severity) and CCL3L1 (marker for MoAM) is not restricted to one cluster in all three datasets." (PMID 34458692, 2021). "For instance, IL1B, NFKB1, NLRP3, PYCARD, and CASP1 are listed in the COVID-19 Disease Map, while there are molecules absent from it, including CCL3, 3L1, 4L2, CXCL1, 2, 3, 5, 16, TNFAIP6, C15orf48, TMEM176A/B, NFE2, PADI4, RAB20, ETS2, PHLDA2, FOLR3, and HP." (PMID 37719701, 2023).
osteoporosis (4 papers, 2011 to 2025). A condition of reduced bone mass, with decreased cortical thickness and a decrease in the number and size of the trabeculae of cancellous bone (but normal chemical composition), resulting in increased fracture incidence. "TNF alpha induced protein 6 (TNFAIP6) is implicated in bone loss and the pathology of osteoporosis in aging." (PMID 35757392, 2022). "It was also found that TNFAIP6 was involved with aging related osteoporosis as its expression changes as the person get older." (PMID 39497989, 2024).
bacterial sepsis (3 papers, 2013 to 2019). "TNFAIP6 is known to be upregulated in response to many proinflammatory mediators (e.g. TNFa) and high levels of TNFAIP6 have been reported in the plasma of patients with bacterial sepsis." (PMID 23874546, 2013).
bladder cancer (3 papers, 2020 to 2025). "Similarly, TNFAIP6 expression has been reported as an independent adverse prognosis marker in the GSE32894 bladder cancer cohort." (PMID 40792276, 2025).
glioma (3 papers, 2022 to 2024). A benign or malignant brain and spinal cord tumor that arises from glial cells (astrocytes, oligodendrocytes, ependymal cells). "Of interest also, TNFAIP6 was identified among ARL4C and MSN as a neural progenitor cell-associated chemoradiotherapy resistance gene set for the prognosis of glioma." (PMID 37511403, 2023). "We performed qRT-PCR analysis and found that the expressions of TNFAIP6, PSMB2, IRF4 and IFNAR2 were significantly upregulated in glioma tissues (n = 30) compared to normal brain tissues (n = 10)." (PMID 36712869, 2022).